CD4 (CD4 molecule)
Diseases named in the same sentence as CD4 in open-access papers (continued):
Sharing a sentence is not in itself a finding about the gene and the disease.
dermatomyositis (25 papers, 2011 to 2025). Dermatomyositis (DM) is a type of idiopathic inflammatory myopathy characterized by evocative skin lesions and symmetrical proximal muscle weakness. "The findings of hyperintense muscles in T2-weighted sequences of brachial contrast-enhanced magnetic resonance imaging and the infiltration of lymphocytic cells and CD4-positive lymphocytes from muscle biopsy were compatible with the diagnostic criteria for dermatomyositis." (PMID 33745453, 2021). "Flow cytometry immunophenotyping was able to differentiate people with anti-synthetase syndrome from those with dermatomyositis, inclusion body myositis and healthy controls, owing to their increased proportion of Effector Memory CD4 T cells." (PMID 40766316, 2025). "We found that both polymyositis and dermatomyositis can reduce the expression of CD28 on secreting CD4 regulatory T cell in B cell panel." (PMID 39470507, 2024). "While CD8+ T cells seem to be important in the pathogenesis of polymyositis and inclusion body myositis, CD4+ T cells and B cells play a predominant role in the pathogenesis of dermatomyositis." (PMID 33071827, 2020). "In polymyositis, there is a predominance of CD8+ T cells, whereas in dermatomyositis CD4+ T cells predominate, along with plasmacytoid dendritic cells and B cells." (PMID 31415030, 2019). "Polymyositis (PM) and dermatomyositis (DM) are chronic inflammatory diseases affecting skeletal muscle with infiltration of mononuclear cells, such as CD4 and CD8 T cells and macrophages." (PMID 22394569, 2012). "Furthermore, double immunofluorescence staining of CD4 and UBASH3A in CD4+ T cells from lymph nodes showed weaker UBASH3A staining in RA patients compared with dermatomyositis patients." (PMID 36324153, 2022). "IIMs are characterized by high levels of circulating cytokines and chemokines, as well as by inflammatory cellular infiltrates, including macrophages, DCs, CD8+ T cells (predominantly affecting the endomysium in polymyositis) and CD4+ T cells, which affect the perimysium in dermatomyositis." (PMID 33071827, 2020). "In DM patients, the frequencies of circulating CD4+ PD-1+ cells are remarkably enhanced and are an accurate dermatomyositis biomarker for diagnosis and bad prognosis (AUC = 0.79)." (PMID 40150045, 2025). "Polymyositis (PM) is mainly infiltrated by CD8+ T cells in the endomysium, while dermatomyositis (DM) is primarily infiltrated by CD4+ T cells in the epimysium." (PMID 36033387, 2022). "IBM cases had significantly more CD4+ cells compared to all dystrophy cases and controls (p ≤ 0.003) and significantly more CD8+ cells compared to all other diagnoses including dermatomyositis cases (p ≤ 0.006)." (PMID 35135626, 2022). "CD4+ T cells are of crucial importance in the occurrence and development of dermatomyositis (DM)." (PMID 35711463, 2022). "RNA-sequencing was conducted on CD4+ T cells (polymyositis = 8 and dermatomyositis = 7) and CD8+ T cells (polymyositis = 4 and dermatomyositis = 5) isolated from peripheral blood mononuclear cells." (PMID 31415030, 2019). "Muscle biopsies from 32 dysferlinopathy, 30 calpainopathy, 30 Becker muscular dystrophy, and 30 inflammatory myopathies (15 each of dermatomyositis and inclusion body myositis) were analyzed through digital quantitation of CD3, CD4, CD8, CD20, and PU.1 immunostaining." (PMID 35135626, 2022). "Moreover, numerous CD4+ and CD8+ T lymphocytes with the phenotype of terminally differentiated cells have been observed in polymyositis and dermatomyositis patients." (PMID 33071827, 2020). "In addition, CD4+CD28- and CD8+CD28- T cells are the predominant T cells that infiltrate inflamed muscles in patients with dermatomyositis and polymyositis, secreting IFN-γ on CMV-specific antigenic stimulation." (PMID 21473750, 2011). "Perforin-expressing CD4+/CD8+ T cells are one of the main immune cell types found in polymyositis (PM) and dermatomyositis (DM)." (PMID 33806895, 2021).
dermatomyositis (continued). "Routine blood tests and clinical manifestations revealed that CD3+CD4+ T cell levels and the development of hypoxemia at the beginning of the disease were positively correlated with mortality in patients with anti-MDA5 antibody-positive dermatomyositis, which may indicate a poor prognosis." (PMID 35992549, 2022).
diffuse large B-cell lymphoma (25 papers, 2010 to 2026). "The aim of the study was to investigate the relationship between PD‐1 expression on the surface of CD4+ T cells and prognosis of patients with diffuse large B‐cell lymphoma (DLBCL)." (PMID 27709793, 2016). "Among the NHL cases, mean CD4 counts was highest for Burkitt's (210 cells/mm3: SD 119), lower for diffuse large B cell lymphoma (154 cells/mm3: 153) and other types (145 cells/mm3: SD 127), and lowest for primary NHL of the brain (77 cells/mm3: SD 105)." (PMID 21143940, 2010). "Furthermore, our analysis of TcEV in diffuse large B-cell lymphoma revealed increased EV secretion in CD4+ T exhausted cells compared to healthy controls." (PMID 40036846, 2025). "The current work tracked immunohistochemistry marker CD4, CD8, CD68, and MMP9 staining in diffuse large B cell lymphoma cases." (PMID 35083113, 2022). "Increased expression of PD-1 in blood-derived CD4+ T cells has been reported for CLL and other B-cell non-Hodgkin lymphomas (B-NHL), including diffuse large B-cell lymphoma (DLBCL)." (PMID 33526861, 2021). "Diffuse Large B-Cell Lymphoma (DLBCL) is known to have lower expression of CD3+ and CD4+ tumor infiltrating lymphocytes (TILs) as well as lower PD-L1 expression as compared to HL." (PMID 37920162, 2023).
epilepsy (25 papers, 2013 to 2026). A brain disorder characterized by episodes of abnormally increased neuronal discharge resulting in transient episodes of sensory or motor neurological dysfunction, or psychic dysfunction. "Understanding the dynamic interplay between microglia and CD4+ T cells in TLE is crucial for deciphering the mechanisms underlying central inflammation in epilepsy, exploring therapeutic avenues to modulate inflammatory responses, and mitigating the effects of seizures." (PMID 39136073, 2024). "Pro-inflammatory CD4+ T cells could also cause neuronal damage in vivo and directly lead to intractable seizure in an animal model of epilepsy partly through secreting interleukin-17A and granulocyte-macrophage colony-stimulating factor." (PMID 36330432, 2022). "In epilepsy patients, Activated microglial cell, Antigen‐presenting cell, CD4+ T cell, demyelinating microglial cell, M1 microglial cell, M1 macrophage, naive B cell and cytotoxic T cell were upregulated." (PMID 41466027, 2026). "Recurrent URTI and LRTI, truncus arteriosus, epilepsy, dysgammaglobulinemia, impaired antibody response to antigens, inverted CD4+/CD8+ ratio." (PMID 41583441, 2025). "In our study, another noteworthy peripheral immune cell was the T cell, where we observed a reduction in activated memory CD4+ T cells and γδ T cells, reflecting the involvement of adaptive pro‐inflammatory immunity in epilepsy." (PMID 39753851, 2025). "Pervious study has showed that epilepsy patients had a relative increase of total leukocytes, neutrophil leukocytes, total lymphocytes, NK cells, epinephrine, and decreased CD4+ T cells in the immediate postictal state." (PMID 39911741, 2024). "Compared to the normal control group, the CD4+ T cell transmigration rate was significantly increased in the epilepsy group." (PMID 39136073, 2024). "The proportion of CD4-naïve T cells, gamma delta T cells, M1 macrophages, and neutrophils was higher in the control group than the epilepsy group." (PMID 38020614, 2023). "Compared with the normal group, the CD4-naïve T cells, gamma delta T cells, M1 macrophages, and neutrophils showed low expression in the epilepsy group." (PMID 38020614, 2023). "We found that CD4-naïve T cells, gamma delta T cells, M1 macrophages, and neutrophils exhibited higher expression in the control group than in the epilepsy group." (PMID 38020614, 2023). "Some studies have substantiated the effects of peripheral immune cells in the resected epileptic foci of pediatric and adult epilepsy patients; and in the infiltrated proinflammatory T cells, CD4+ T cells predominated." (PMID 37435496, 2023). "A previous study found an expansion of the CD4 T-cell subset in the peripheral blood and a shift toward a proinflammatory Th17/Th1 CD4 T-cell immune profile in drug-resistant epilepsy." (PMID 37365625, 2023). "It has been reported that immunodeficient (depletion of T cells CD4) mice exhibited significant shortening of the latent stage before epilepsy onset, suggesting the protective effect of T cells in epileptogenesis." (PMID 36389252, 2022). "Pastick’s study found that a CD4+ T-cell count of < 50 cells/μL was an important predictor of epilepsy in patients with HIV/CM." (PMID 34376147, 2021). "A 48 year old man with a diagnosis of HIV infection since 1993, on highly active anti-retro viral therapy (HAART) with stable CD4 count and undetectable viral load for years and seizure disorder presented with recurrent drowsiness." (PMID 24222872, 2013). "Notably, in patients with epilepsy, the peripheral immune environment exhibits a marked increase in activated mast cells and memory B cells, accompanied by significant decreases in CD4 memory activated T cells and γδ T cells." (PMID 39753851, 2025). "In addition, several studies conducted on the changes in the circulating T lymphocytes, including CD4+ T lymphocytes and CD8+ T lymphocytes, suggested a possible association between epilepsy and lymphocytes." (PMID 39723425, 2024).
epilepsy (continued). "Consequently, the infiltration of CD4+ T cells into the CNS influences pro‐epileptic central inflammation by microglia in response to epilepsy." (PMID 39136073, 2024). "The crucial roles played by Th1/Th2 cells in the periphery reflect the microglia state dynamic in the CNS, and the ensuing interaction between these CD4+ T cells and microglia significantly contributes to the inflammatory response driving the progression of epilepsy." (PMID 39136073, 2024). "Moreover, the study identified that CD4 T cells in the peripheral blood are present in a higher proportion of epilepsy patients, which means CD4 T cells may play an important role in the occurrence and development of epilepsy." (PMID 38020614, 2023). "The result indicated that there was a significantly increased abundance of macrophages and a decreased abundance of CD4 and CD8 T cell in epilepsy group, compared with HC group among the 10 immune cell subtypes." (PMID 39911741, 2024). "Overall, macrophages, CD4 and CD8 T cell subtypes were the immune cells that underwent the most significant abundance changes in epilepsy and were significantly correlated with the expression level of hub ARDEGs." (PMID 39911741, 2024). "As hippocampal sclerosis is an indication for epilepsy surgery, studies utilizing surgically resected HS tissues also suggested peripheral CD8+ and/or CD4+ T cell infiltration into the hippocampi, the perivascular region, or diffusely in the brain parenchyma." (PMID 35844577, 2022). "Several original or meta- analysis on epilepsy patients reported up-regulated IL-1α, IL-17, IFN-α, CCL4, CCL11, CXCL10, CX3CL1, HMGB1, bFGF and down-regulated CD4+ percentage in the peripheral blood." (PMID 35844577, 2022). "In six (43%) children, the CD4 percentage was < 25%, even though they had been on ART for at least 7 months at the time of diagnosis of epilepsy." (PMID 32670626, 2020). "Epilepsy patients exhibited an altered peripheral immune profile, notably with increased activated mast cells and decreased CD4 memory activated T cells and γδ T cells." (PMID 39753851, 2025). "In addition, among the 10 immune cell subtypes, there was a significantly increased abundance of macrophage and a decreased abundance of CD4 and CD8 T cell in epilepsy group, compared with HC group." (PMID 39911741, 2024). "The immune infiltration analysis showed that there was a significantly increased abundance of macrophages and a decreased abundance of CD4 and CD8 T cells, including Tr1, nTreg, Tfh, CD8 naïve, cytotoxic T cells and effector memory T cells in the epilepsy group." (PMID 39911741, 2024). "Personality characteristics were stronger determinants of HRQOL than sociodemographic factors such as age, social integration and income as well as clinical factors such as comorbidity, CD4+ counts and HIV disease stage and seizure outcome after epilepsy surgery." (PMID 28355244, 2017).
sarcopenia (25 papers, 2018 to 2026). Progressive decline in muscle mass due to aging which results in decreased functional capacity of muscles. "CD4 + T-cell count ≤ 200 cells/mm3 were associated with sarcopenia in both constructs (adjusted OR ≈ 4)." (PMID 41877037, 2026). "Although there are limited studies explaining the association between sarcopenia risk and low CD4 T-cell count, systemic inflammation and increased immune activation caused by disease progression contribute to muscle mass loss and sarcopenia development." (PMID 39752996, 2025). "We found an association with senescent CD4 T cells and hospital readmission as well as total hospital time, as well as a striking association with sarcopenia as measured by muscle attenuation." (PMID 40144851, 2025). "Although many authors have studied CD8 T cells in the context of aging, we observed in our study a more striking relationship between CD4 T cell maturation subtypes as a predictor of clinical outcomes and as associated with both frailty and sarcopenia." (PMID 40144851, 2025). "This association with sarcopenia, with decreased muscle attenuation seen in patients with increased frequency of senescent cells, was observed for both CD4 and CD8 T cells." (PMID 40144851, 2025). "In contrast, TEMRA CD4 T cells were significantly associated with sarcopenia by muscle attenuation by linear regression (p = 0.011)." (PMID 40144851, 2025). "Chi‐square and Fisher's exact tests revealed significant associations between CD3+/CD4+ cell–myosteatosis and sarcopenia (P < 0.001)." (PMID 38894548, 2024). "Different definitions of sarcopenia were independently associated with age, education level, current CD4 count and/or polypharmacy." (PMID 36176015, 2022). "We have identified older age, lower education level, lower current CD4 count and presence of polypharmacy as risk factors associated with sarcopenia." (PMID 36176015, 2022). "From the results above, we found that the levels of naïve CD4+ T cells and memory CD4+ T cells resting were decreased in both AP and sarcopenia, while mast cell resting increased." (PMID 40785039, 2025). "Senescent CD4 and CD8 T cells were significantly associated with sarcopenia (p = 0.009 and p = 0.006, respectively)." (PMID 40144851, 2025). "When specialised in plasma cells, patients with sarcopenia had lower levels of naïve CD4+ T cells, memory CD4+ T cells resting, gamma delta T cells, NK cells activated and neutrophils, compared with healthy individuals." (PMID 40785039, 2025). "Elevated levels of eosinophils, mast cells, monocytes, and natural killer cells were observed in sarcopenia patients, whereas levels of γδT cells, macrophages, natural killer T cells, and effector memory CD4 T cells were decreased." (PMID 39777262, 2024). "Studies indicate a substantial decrease in peripheral blood CD3+ and CD4+ T cell counts in HCC patients with sarcopenia." (PMID 38698848, 2024). "Older age, lower education level and lower CD4 count have previously been shown to correlate with sarcopenia or low muscle mass." (PMID 36176015, 2022). "In this study, peripheral blood T lymphocytes, especially CD3+ and CD4+ T-cell counts, were significantly reduced in patients with sarcopenia." (PMID 35463384, 2022). "The lymphocyte count, CD3+, CD4+, and CD8+ were statistically significantly lower among patients with a high risk sarcopenia than those with lower risk." (PMID 34112103, 2021). "The most significant canonical pathway based on sarcopenia-related DAGs was the antigen presentation pathway (Fisher’s exact test right-tailed p-value <0.0001), particularly antigen presentation to CD4+ T lymphocyte pathway." (PMID 29723245, 2018). "Immunostaining was performed on resected specimens from 23 healthy participants, excluding patients with osteopenia alone and sarcopenia alone, and 37 patients with osteosarcopenia by comparing the numbers of CD4-, CD8-, FOXP3-, PD-1, and PD-L1-positive cells between the groups." (PMID 40445404, 2025).